EIF5A2 (eukaryotic translation initiation factor 5A2)
Description:
Translation factor that promotes translation elongation and termination, particularly upon ribosome stalling at specific amino acid sequence contexts. Binds between the exit (E) and peptidyl (P) site of the ribosome and promotes rescue of stalled ribosome: specifically required for efficient translation of polyproline-containing peptides as well as other motifs that stall the ribosome. Acts as a ribosome quality control (RQC) cofactor by joining the RQC complex to facilitate peptidyl transfer during CAT tailing step (By similarity). Also involved in actin dynamics and cell cycle progression, mRNA decay and probably in a pathway involved in stress response and maintenance of cell wall integrity (By similarity).
Synonyms: eIF-5A2; eIF5AII
Tractability: Antibody: UniProt places it where antibodies can reach, with medium confidence. PROTAC: ubiquitination databases record sites on it.
Gene: Protein-coding gene on chromosome 3 (170,888,418 to 170,908,644, reverse strand). Ensembl gene ENSG00000163577.
Subcellular location: Cytoplasm; Nucleus; Endoplasmic reticulum membrane
Subcellular location (Human Protein Atlas): Vesicles
Pathways (Reactome):
Metabolism of proteins: Hypusine synthesis from eIF5A-lysine
Gene Ontology:
Molecular function: protein binding; translation elongation factor activity; ribosome binding; RNA binding
Biological process: spermatogenesis; translational elongation
Cellular component: cytoplasm; cytosol; endoplasmic reticulum membrane; nucleus
Genetic constraint (gnomAD): Loss-of-function variants: 10 observed, 13.03 expected, observed/expected ratio (o/e) 0.77, 90% interval 0.47 to 1.3. The upper end of that interval is the gene's LOEUF score, 1.3, which puts it in group 5 of 6, group 1 being the genes least tolerant of losing a copy. Missense variants: 114 observed, 146.64 expected, observed/expected ratio (o/e) 0.78, 90% interval 0.67 to 0.91. Synonymous variants: 39 observed, 48.91 expected, observed/expected ratio (o/e) 0.8, 90% interval 0.62 to 1.04.
Homologues: Orthologues: chimpanzee EIF5A2 (100% identical), macaque EIF5A2 (100% identical), mouse Eif5a2 (100% identical), pig EIF5A2 (100% identical), rat Eif5a2 (100% identical), guinea pig EIF5A2 (86% identical), zebrafish eif5a (78% identical), zebrafish eif5a2 (77% identical), tropical clawed frog eif5a (75% identical), Drosophila melanogaster eEF5 (67% identical), Caenorhabditis elegans iff-2 (61% identical), Caenorhabditis elegans iff-1 (57% identical). Paralogues in human: EIF5A (82% identical), EIF5AL1 (80% identical).
Diseases named in the same sentence as EIF5A2 in open-access papers:
EIF5A2 is named in the same sentence as 65 diseases in open-access papers, as found by Europe PMC text mining. Sharing a sentence is not in itself a finding about the gene and the disease. The quoted sentences say what the papers report.
ovarian carcinoma (27 papers, 2002 to 2025). A malignant neoplasm originating from the surface ovarian epithelium. "Here we report that EIF5A2 is highly expressed in ovarian cancers and associated with patient poor survival." (PMID 33827661, 2021). "Previously, we showed that overexpression of eIF-5A2 at the protein level was significantly associated with the advanced stages of ovarian cancer." (PMID 21612665, 2011). "For example, eIF4E overexpression is frequently found in patients with colorectal cancer (CRC) or breast cancer (BC); eIF5A2 overexpression is obviously associated with the advanced stage of ovarian cancer; eIF3D increases cell cycle progression and motility in prostate cancer (PCa)." (PMID 34016142, 2021). "According to the previous study, eIF5A2 (located at 3q26.2), has been significantly associated with the advanced stage of ovarian cancer and has been described as an adverse prognostic marker of survival in stage I non-small cell lung cancer patients and localized invasive bladder cancer." (PMID 27549330, 2016). "For example, lncRNA RAD51-AS1 promotes the progression of ovarian cancer by sponging miR-140-3p to regulate EIF5A2 expression." (PMID 39951205, 2025). "Researchers have demonstrated that oncogenes PIK3CA, MCL1, MYCN, DHFR, and eIF-5A2 were over-amplified via eccDNA in primary ovarian cancers, ovarian cancer cell line UACC-1598 and cervical cancer cell line HeLa, respectively." (PMID 37233789, 2024). "Our data indicate that EIF5A2 forms a positive feedback loop with TGFβ pathway in ovarian cancer cells." (PMID 33827661, 2021). "To verify the expression of EIF5A2 in ovarian cancer tissues, we performed immunofluorescent staining on sections from three ovarian serous carcinoma patients that had been verified by H&E staining." (PMID 33827661, 2021). "Expression of EIF5A2 was significantly higher in peritoneal MCAs/MCSs compared to matched primary tumors, and EIF5A2 was also unregulated in ovarian cancer cell line-derived spheroids." (PMID 33726845, 2021). "Since we found that EIF5A2 promoted EMT in ovarian cancer cells, we also determine the role of EIF5A2 in migration and invasion of ovarian cancer cells using Transwell plates." (PMID 33827661, 2021). "We further demonstrate that EIF5A2 promotes EMT by activating the TGFβ pathway and KO of EIF5A2 inhibits ovarian tumor growth and metastasis in orthotopic ovarian cancer mouse models." (PMID 33827661, 2021). "To determine the role of EIF5A2 in ovarian cancer cells, we examined cell survival in EIF5A2 KO SKOV3 and OVCAR8 cells, EIF5A2 OE OVCAR3 cells and control cells using cell colony formation assay." (PMID 33827661, 2021). "Our results indicated that loss of EIF5A2 suppressed primary ovarian tumor growth and tumor metastasis by inhibiting EMT and attenuating the TGFβ pathway in orthotopic ovarian cancer mouse models." (PMID 33827661, 2021). "In ovarian cancer, EIF5A2 elucidated the oncogenic role in the development of ovarian cancer and is considered as an independent predictor of outcome in patients with ovarian carcinoma." (PMID 33726845, 2021). "To assess the expression of EIF5A2 in ovarian cancer, we analyzed 607 serous ovarian carcinomas and 561 normal tissues including 130 ovaries, plus 431 blood samples in the Oncomine database." (PMID 33827661, 2021). "RNA-sequencing (RNA-seq) was used to reveal the mechanism by which EIF5A2 positively modulates the stem-like properties of ovarian cancer cells." (PMID 33726845, 2021). "Together, these results suggest that EIF5A2 positively modulates stem-like characteristics in ovarian cancer cells." (PMID 33726845, 2021). "We also examined an additional 415 ovarian carcinoma including 207 EIF5A2 high and 208 low in the SurvExpress database." (PMID 33827661, 2021). "Lentiviral CRISPR/Cas9 nickase vector mediated knockout (KO) of EIF5A2 inhibits epithelial to mesenchymal transition (EMT) in SKOV3 and OVCAR8 ovarian cancer cells that express high levels of EIF5A2." (PMID 33827661, 2021).
ovarian carcinoma (continued). "Our studies indicated a positive feedback loop between EIF5A2 and the TGFβ pathway in ovarian cancer cells." (PMID 33827661, 2021). "We also analyzed EIF5A2 expression in multiple cancer types from TCGA database, and EIF5A2 was amplified across multiple cancer types with the highest percentage found in specimens from lung and ovarian cancer patients." (PMID 33827661, 2021). "In UACC-1598 cells, an ovarian cancer cell line, the cell growth rate was inhibited by antisense DNA sequence against EIF5A2." (PMID 32368188, 2020). "According to eIF5A2 protein level in ovarian carcinoma tissues, patents with higher eIF5A2 protein levels had aggressive clinicopathologic features and poor survival." (PMID 32368188, 2020). "EIF5A2, an isoform of eIF5A and located on chromosome 3q26, was first discovered in ovarian carcinoma and has been identified as a novel oncogene in many human cancer cells." (PMID 30175116, 2018). "For example, increased EIF5A2 expression is an independent molecular marker for reduced survival in patients with ovarian carcinoma 22 and EIF4E is a useful marker for malignant transformation of cervical squamous cells." (PMID 28203520, 2016). "In ovarian carcinoma, overexpression of eIF5A2 was detected in 7% cystadenomas, 30% borderline tumors, and 53% invasive carcinomas, as opposed to normal expression in normal ovaries." (PMID 28083147, 2016). "eIF5A's isoform eIF5A2 is upregulated in various cancer types including hepatocellular carcinoma, ovarian carcinoma, and colorectal carcinoma (CRC)." (PMID 28083147, 2016). "Recent studies have reported that eIF5A2 is aberrantly expressed in several types of tumor cells, including rectal carcinoma, gastric cancer, ovarian cancer, bladder cancer, and colon cancer." (PMID 27028999, 2016). "Overexpression of EIF5A2 has been detected in many solid tumors, including ovarian cancer, hepatocellular carcinoma, non-small cell lung cancer, bladder cancer, melanoma, colorectal cancer, pancreatic adenocarcinoma and ESCC." (PMID 26317793, 2015). "Upregulation of eIF5A2 has been reported in many cancers including ovarian cancer, hepatocellular carcinoma, and bladder cancer." (PMID 26581310, 2015). "Among them, EIF5A2 (eukaryotic initiation factor 5A2) is a candidate oncogene isolated from the amplified region at 3q in ovarian cancer." (PMID 26214687, 2015). "To date, two human isoforms of eIF5A have been identified (eIF5A1 and eIF5A2) and amplification of the eIF5A2 gene has been found in ovarian cancer." (PMID 11953842, 2002). "Studies have demonstrated that EIF5A2 expression is elevated in ovarian cancer, cervical cancer, gastric cancer, lung cancer, liver cancer, and other cancers, and plays a pivotal role in many biological processes, such as tumor formation, growth, and metastasis." (PMID 40964657, 2025). "We investigated the relationship between the three subtypes and various well‐known oncogenic genes and tumour suppressors in ovarian cancer from cBioPortal and found EIF5A2 (P < 0.001), FGF1 (P < 0.001) and EGFR (P = 0.002) were highly expressed in the CAFs‐immune subtype." (PMID 33522069, 2021). "In support of this hypothesis, we found that KO of EIF5A2 not only inhibited primary ovarian tumor growth and clonogenicity but also ovarian tumor metastasis in orthotopic ovarian cancer mouse models." (PMID 33827661, 2021). "Phospho- and total SMAD2 in EIF5A2 KO and control ovarian cancer cells was examined by WB." (PMID 33827661, 2021). "To determine whether EIF5A2 contributes to primary ovarian tumor growth and metastasis in vivo, we injected 5 × 105 ovarian cancer SKOV3 KO and control cells intrabursally into two-month-old immunocompromised NSG female mice." (PMID 33827661, 2021). "Thus, EIF5A2 expression correlated well with poor ovarian patient survival indicating a potential predictive biomarker for ovarian cancer diagnosis." (PMID 33827661, 2021).
ovarian carcinoma (continued). "Interestingly, EIF5A2 is aberrantly amplified or upregulated in various cancers including ovarian cancer, lung, pancreatic cancer, and hepatocellular carcinoma, and contributes to tumor growth and metastasis." (PMID 33827661, 2021). "However, the role of EIF5A2 in chemo-resistance, stemness, and corresponding regulatory mechanisms in ovarian cancer remains elusive." (PMID 33726845, 2021). "We also examined EIF5A2 expression from Clinical Proteomic Tumor Analysis Consortium (CPTAC) database including 100 specimens from ovarian cancer patients and 25 normal ovaries that also showed significantly higher protein expression in ovarian cancer tissues than that in normal ovaries." (PMID 33827661, 2021). "While EIF5A2 has oncogenic activity in several cancers and contributes to tumor metastasis, its role in ovarian cancer is unknown." (PMID 33827661, 2021). "Our results imply that EIF5A2 positively regulates stemness in ovarian cancer cells via E2F1/KLF4 pathway and may serve as a potential target in CSCs-targeted therapy for ovarian cancer." (PMID 33726845, 2021). "In particular, EIF5A2 is correlated with the poor survival of ovarian cancer patients." (PMID 33827661, 2021). "Although we showed that EIF5A2 promoted EMT in ovarian cancer cells, the molecular mechanisms by which EIF5A2 regulates EMT remains unclear." (PMID 33827661, 2021). "It has been identified as an oncogene in ovarian cancer, suggesting that aberrant expression of eIF5A2 may be responsible for the malignant behavior of cancer cells." (PMID 26581310, 2015). "eIF-5A was found to be overexpressed in samples from colorectal adenoma and eIF-5A2 is present in various cancer cell lines and its overexpression may serve as a prognostic marker in patients with urothelial carcinoma or ovarian cancer." (PMID 22927971, 2012). "EIF5A2 may act as a potential modulator in maintaining CSC-like property of ovarian cancer cells." (PMID 33726845, 2021). "Using gain- and loss-of-function approaches through lentiviral vector-based gene editing and overexpression, we showed for the first time that EIF5A2 promotes EMT in ovarian cancer cells, suggesting that it may contribute to ovarian cell invasion and metastasis." (PMID 33827661, 2021). "Additionally, eIF-5A and/or eIF-5A2 have been proposed as a transforming and predictive factor in the development of hepatocellular carcinoma, non-small cell lung cancer and in patients with ovarian carcinoma." (PMID 22927971, 2012). "Recently, eIF5A2 overexpression has been reported in a variety of solid tumors, including NSCLC, ovarian cancer, pancreatic cancer, CRC, BCA, hepatocellular carcinoma, and esophageal squamous cell carcinoma (ESCC)." (PMID 35931669, 2022). "To understand how EIF5A2 contributed to EMT in ovarian cancer cells, we examined the potential co-regulation between EIF5A2 and TGFβ pathway in ovarian cancer cells by exposing both SKOV3 and OVCAR8 cells with 6 ng/ml TGFβ." (PMID 33827661, 2021). "We then examined the expression of EIF5A2 in highly-invasive SKOV3 and OVCAR8 ovarian cancer cells, and low-invasive OVCAR3 cells using WB blot." (PMID 33827661, 2021). "KO of EIF5A2 in SKOV3 and OVCAR8 cells inhibits ovarian cancer cell migration and invasion, while its overexpression promotes cell migration and invasion in OVCAR3 adenocarcinoma cells." (PMID 33827661, 2021). "EIF5A2, the member of the EIF family, is a novel oncogene and up-regulated in ovarian cancer, esophageal cancer, gastric cancer, etc.." (PMID 32466797, 2020). "Although EIF5A2 is upregulated in ovarian cancer, its functional role has not been characterized at the mechanistic level." (PMID 33827661, 2021). "Therefore, targeting EIF5A2 may inhibit tumor metastasis and overcome chemoresistance by reversing EMT in ovarian cancer cells." (PMID 33827661, 2021).
hepatocellular carcinoma (25 papers, 2011 to 2024). A malignant tumor that arises from hepatocytes. "EIF5A2 has been reported to be associated with ovarian cancer, colorectal carcinoma, hepatocellular carcinoma, breast cancer, bladder cancer, non-small cell lung cancer, gastric cancer, prostate cancer, and nasopharyngeal carcinoma." (PMID 32605067, 2020). "EIF5A2 was shown to associate with metastasis, developmental stages, histological types and poor patient survival in gall bladder cancer, oral squamous cell carcinoma, prostate cancer, cervical cancer, and hepatocellular carcinoma." (PMID 33827661, 2021). "For example, N1-guanyl-1,7-diaminoheptane (GC7), an inhibitor of eIF5A2, reduced doxorubicin resistance in hepatocellular carcinoma cells by reversing hypoxia-induced EMT through the HIF-1α signaling pathway." (PMID 35931669, 2022). "EIF5A2 mRNA is upregulated in several human tumor cell types such as pancreatic ductal adenocarcinoma, hepatocellular cancer, lung cancer, colorectal cancer, and gastric cancer, indicating that eIF5A2 is a potential oncogene." (PMID 34864817, 2021). "In hepatocellular carcinoma, the overexpression of EIF5A2 activates the RhoA/Rac1 signaling pathway to stimulate cytoskeleton rearrangement." (PMID 32605067, 2020). "Eukaryotic initiation factor 5A2 (EIF5A2), located on chromosome 3q26, has also been described to be involved in a variety of cancers, including colorectal cancer, hepatocellular cancer, ovarian cancer, and bladder cancer." (PMID 27376958, 2016). "eIF-5A2 was originally identified as a proto-oncogene whose overexpression leads to cancerous transformation of hepatocellular carcinoma cell lines, and contributes to cancer progression and metastasis." (PMID 21612665, 2011). "eIF5A2 modulated the metastasis and invasion of hepatocellular carcinoma." (PMID 35874632, 2022). "In hepatocellular carcinoma cells in vivo, eIF5A2 suppression attenuates tumorigenic properties." (PMID 28083147, 2016). "Previous studies have confirmed that eIF5A2 is upregulated in various cancer types, such as gastric cancer, bladder cancer, hepatocellular carcinoma (HCC), and colon cancer." (PMID 30175116, 2018). "Furthermore, it is suggested that eIF5A2 may serve as prognostic biomarker for poor survival of hepatocellular carcinoma patients." (PMID 26581310, 2015). "Recently, the ablation or inhibition of EIF5A2 was also reported to enhance the chemosensitivity of HCC (hepatocellular carcinoma) cells to 5-fluorouracil (5-FU)/doxorubicin and breast cancer cells and bladder cancer cells to doxorubicin." (PMID 26317793, 2015). "In hepatocellular carcinoma (HCC), mRNA level of EIF5A2 was upregulated in more than half of HCC clinical samples." (PMID 32368188, 2020). "Here, we investigated the effects of ROS on the eIF5A2-induced epithelial-mesenchymal transition (EMT) and migration in six hepatocellular carcinoma (HCC) cell lines." (PMID 27028999, 2016). "It was also reported that EIF5A2 could promote tumor metastasis and angiogenesis in ESCC and hepatocellular carcinoma." (PMID 26317793, 2015). "In 2013, they showed that the inhibition of eIF5A2 by knockdown or N1-guanyl-1,7-diaminoheptane treatment prevented EMT and downstream doxorubicin resistance in hepatocellular carcinoma (HCC)." (PMID 38139368, 2023). "Enhanced eIF5A2, but not eIF5A1, efficiently triggered the growth of hepatocellular carcinoma." (PMID 33200656, 2020).